EPHB3 (EPH receptor B3)
Description:
Receptor tyrosine kinase which binds promiscuously transmembrane ephrin-B family ligands residing on adjacent cells, leading to contact-dependent bidirectional signaling into neighboring cells. The signaling pathway downstream of the receptor is referred to as forward signaling while the signaling pathway downstream of the ephrin ligand is referred to as reverse signaling. Generally has an overlapping and redundant function with EPHB2. Like EPHB2, functions in axon guidance during development regulating for instance the neurons forming the corpus callosum and the anterior commissure, 2 major interhemispheric connections between the temporal lobes of the cerebral cortex. In addition to its role in axon guidance also plays an important redundant role with other ephrin-B receptors in development and maturation of dendritic spines and the formation of excitatory synapses. Controls other aspects of development through regulation of cell migration and positioning. This includes angiogenesis, palate development and thymic epithelium development for instance. Forward and reverse signaling through the EFNB2/EPHB3 complex also regulate migration and adhesion of cells that tubularize the urethra and septate the cloaca. Finally, plays an important role in intestinal epithelium differentiation segregating progenitor from differentiated cells in the crypt.
Synonyms: EK2; hEK2; ETK2; TYRO6
Tractability: Small molecule: an approved drug acts on it; a structure with a bound ligand is known; a high-quality ligand is known; it belongs to a druggable protein family. Antibody: UniProt places it where antibodies can reach, with high confidence; its Gene Ontology location is reachable by antibodies, with high confidence; UniProt predicts a signal peptide or a membrane-spanning region. PROTAC: it is named in the literature on targeted protein degradation; UniProt records ubiquitination sites on it; its protein half-life has been measured; a small molecule that binds it is known.
Target class: Tyrosine protein kinase Eph family; Protein Kinase; TK protein kinase group; Kinase; Enzyme
Gene: Protein-coding gene on chromosome 3 (184,561,776 to 184,582,408, forward strand). Ensembl gene ENSG00000182580.
Subcellular location: Cell membrane; Cell projection, dendrite
Pathways (Reactome):
Developmental Biology: EPH-Ephrin signaling; EPH-ephrin mediated repulsion of cells; EPHB-mediated forward signaling; Ephrin signaling
Gene Ontology:
Molecular function: ephrin receptor activity; protein binding; transmembrane-ephrin receptor activity; ATP binding; axon guidance receptor activity; protein kinase activity; protein tyrosine kinase activity; transmembrane receptor protein tyrosine kinase activity; transmembrane signaling receptor activity
Biological process: cell migration; ephrin receptor signaling pathway; regulation of cell-cell adhesion; substrate adhesion-dependent cell spreading; angiogenesis; axon guidance; axonal fasciculation; corpus callosum development; dendritic spine development; dendritic spine morphogenesis; digestive tract morphogenesis; positive regulation of synapse assembly; regulation of axonogenesis; roof of mouth development; thymus development; urogenital system development; cell surface receptor protein tyrosine kinase signaling pathway; cell-substrate adhesion
Cellular component: plasma membrane; cytosol; dendrite; extracellular region; membrane
Genetic constraint (gnomAD): Loss-of-function variants: 32 observed, 98.74 expected, observed/expected ratio (o/e) 0.32, 90% interval 0.24 to 0.44. The upper end of that interval is the gene's LOEUF score, 0.44, which puts it in group 1 of 6, group 1 being the genes least tolerant of losing a copy. Missense variants: 985 observed, 1,354.7 expected, observed/expected ratio (o/e) 0.73, 90% interval 0.69 to 0.77. Synonymous variants: 482 observed, 535.4 expected, observed/expected ratio (o/e) 0.9, 90% interval 0.83 to 0.97.
Homologues: Orthologues: macaque EPHB3 (99% identical), dog EPHB3 (99% identical), pig EPHB3 (98% identical), chimpanzee EPHB3 (98% identical), guinea pig EPHB3 (97% identical), mouse Ephb3 (96% identical), rabbit EPHB3 (96% identical), rat Ephb3 (96% identical), tropical clawed frog ephb3 (77% identical), zebrafish ephb3a (68% identical), zebrafish ephb3b (43% identical). Paralogues in human: EPHB1 (70% identical), EPHB2 (69% identical), EPHA4 (57% identical), EPHB4 (57% identical), EPHA5 (56% identical), EPHA3 (55% identical), EPHA7 (54% identical), EPHA6 (54% identical), EPHA8 (50% identical), EPHA2 (47% identical), EPHA1 (43% identical), EPHA10 (42% identical), and 41 more.
Diseases named in the same sentence as EPHB3 in open-access papers:
EPHB3 is named in the same sentence as 66 diseases in open-access papers, as found by Europe PMC text mining. Sharing a sentence is not in itself a finding about the gene and the disease. The quoted sentences say what the papers report.
colorectal cancer (16 papers, 2008 to 2025). A primary or metastatic malignant neoplasm that affects the colon or rectum. "Moreover, the related ephrinB3 (EPHB3), a Paneth cell marker and tumor suppressor, has recently been linked in cell line models of human colorectal cancer to transcriptional suppression specifically by TCF7L1." (PMID 32403323, 2020). "Acquisition of resistance to cetuximab, an antibody-based EGFR inhibitor, is associated with an increase in EphB3 expression levels and EphB3/EGFR binding in colorectal cancer cells." (PMID 38391938, 2024). "EphB3 induction was observed in EGFR-inhibitor-resistant colorectal cancer and FGFR-inhibitor-resistant gastric cancer." (PMID 36291790, 2022). "We aimed to investigate the expression profile of EPHB3 in colorectal precancerous lesions and colorectal cancers (CRCs), and assess its prognostic value." (PMID 32294981, 2020). "The roles of EPHB3 in colorectal cancer (CRC) development have been characterized using CRC mouse models." (PMID 32294981, 2020). "Overall, these results indicate that colorectal cancer is distinct from other cancer types in displaying higher expression of EphrinB2 and its receptors EphB1, EphB2, EphB3, and EphB4." (PMID 31545551, 2019). "We examined the expression of EphrinB2 ligand and the EphrinB2 signaling receptors (EphB1, EphB2, EphB3, EphB4, and EphA4) in colorectal carcinoma." (PMID 31545551, 2019). "To evaluate the effects of EphB2 depletion, we selected the SW620 colorectal carcinoma cell line, which contains abundant EphB2, whereas EphB1, EphB3, and EphB4 are undetectable and EphA4 is detected at low levels." (PMID 31545551, 2019). "Overexpression of EPHB3 in colorectal cancer cells inhibited proliferation in monolayer culture and growth in both soft agar assays and as xenografts." (PMID 20195492, 2010). "Since the EPHB receptors (EPHB2, EPHB3 and EPHB4) follow a similar pattern of transcriptional silencing in colorectal cancers, all EPHB receptor family members probably play a similar role in this disease." (PMID 18682749, 2008). "Consistent with the current results, previous observations noted that EphA2 signaling protects breast cancer cells from death, EphB3 signaling suppresses Fas‐induced apoptosis in T cells, and the kinase inhibitor AZ12672857 reduces the viability of selected colorectal carcinoma cells." (PMID 31545551, 2019). "The HT‐29 colorectal carcinoma cell line, which needs EphrinB2 to survive, contains abundant EphB4 but not EphB1, EphB2, EphB3, or EphA4 proteins, as observed previously." (PMID 31545551, 2019). "In colorectal carcinomas, Snail1 could combine with the competitive displacement of ASCL2 and epigenetic mechanisms to rapidly silence the EPHB3 tumor suppressor." (PMID 31271097, 2019). "In colorectal carcinoma, the expression of miR-149-5p regulated cell growth, migration, and invasion through its targeting of the EPH receptor B3 gene (EphB3), and the knockdown of EphB3 inhibited tumor growth by in vivo assays." (PMID 28902136, 2017). "Together, these findings indicate that activation of EPHB3 is at least partially responsible for reduced HCT116 colorectal cancer cell growth observed in the absence of TCF7L1." (PMID 27333864, 2016).
colon carcinoma (10 papers, 2010 to 2023). "While EPHA4 signaling promotes mesenchymal-to-epithelial transition during morphogenesis in zebra fish embryo development, it was reported that overexpression of EPHB3 enhances cell–cell contacts and inhibits the growth in HT-29 human colon cancer cells." (PMID 37239828, 2023). "Overexpression of EPHB3 in the colon cancer cell line, DLD1, led to decreased cell growth and migration and reduced mitogen-activated protein kinase signaling." (PMID 32294981, 2020). "In contrast, Mak’s group showed that HectH9 decreased Myc and EphB3 expression and suppressed colon tumor development in the APCmin mouse model." (PMID 31201299, 2019). "The relationship of elevated expression of EphB2 and EphB3 with abnormal migration of epithelial cells in the crypt villus junction in colon tumors of mice is suggestive of Eph receptor involvement in colorectal cancer." (PMID 29682554, 2018). "The activation of EphB3 in HT-29 human colon cancer cells inhibits epithelial-to-mesenchymal transition via cell adhesion molecules." (PMID 29682554, 2018). "First, we confirmed the interaction of afadin with EphB3 using Ls174T colon cancer cells, which originate from a human colorectal tumor and expresses endogenous EphB3 and afadin." (PMID 25333284, 2014). "We confirmed here for the first time that afadin interacts with EphB3 in the colon cancer cell line Ls174T." (PMID 25333284, 2014). "Moreover, in vitro studies showed that EPHB3 overexpression attenuated the proliferation and migration of colon cancer cells, and this was probably due to reduced MAP kinase signaling." (PMID 32294981, 2020). "Also, analysis of paired normal colon tissue and colon cancer (n = 26) showed that mRNA levels of EphB2, EphB3, EphB4, and EphA4 are significantly lower in the normal tissue than in the adjacent cancer, whereas levels of EphrinB2 and EphB1 are similar." (PMID 31545551, 2019). "This response was strongest for ephrin-B1 +EphB2 and ephrin-B1 + EphB3 with the response from ephrin-B1 and EphB4 only producing minor modifications in cell distribution and compartmentalization in the DLD1 colorectal adenocarcinoma and Co115 colon carcinoma cells lines used in that study." (PMID 20624275, 2010). "In addition, in another public transcript data set (GSE76342) for the colon cancer cell line LoVo with or without metformin treatment, we found that metformin inhibited expression of the CSC markers Lgr5, ASCL2, EPHB3, OLFM4, BMI1, Lrig1, TERT, CD44, and CD133." (PMID 32911743, 2020).
gastric cancer (9 papers, 2020 to 2025). A primary or metastatic malignant neoplasm involving the stomach. "Therefore, exosomal circRELL1 regulated gastric cancer progression by regulating autophagy activation through the miR-637/EPHB3 axis." (PMID 40936702, 2025). "In addition, increased expression of this lncRNA in gastric cancer patients can predict poor prognosis and promotes tumorigenesis by epigenetically silencing EphB3 (EPH receptor B3) via EZH2 and LSD1, also known as KDM1A (lysine demethylase 1A)." (PMID 32760219, 2020). "In gastric cancer (GC), upregulation of FOXD2-AS1 promotes carcinogenesis by epigenetically silencing EPHB3 via recruiting EZH2 and LSD1, leading to H3K27 methylation and H3K4 demethylation, respectively." (PMID 34461912, 2021). "Specifically, in gastric cancer (GC), the heightened expression of FOXD2-AS1 facilitates carcinogenesis by orchestrating the epigenetic silencing of EPHB3." (PMID 38274897, 2023). "Additionally, in gastric cancers EZH2, a methyltransferase and the core catalytic subunit of polycomb repressive complex 2, may mediate the epigenetic suppression of EPHB3." (PMID 32294981, 2020).
adenoma (6 papers, 2010 to 2022). A neoplasm arising from the epithelium. "Enhanced EPHB3 expression significantly declined during the transformation from adenoma to carcinoma and as the tumor invaded into deeper tissue layers." (PMID 32294981, 2020). "We found that enhanced EPHB3 expression in adenoma significantly decreased during the transformation to carcinoma, and it declined further when cancer cells invaded into the muscular layers." (PMID 32294981, 2020). "EPHB3 expression was significantly lower in the carcinoma regions (mean H-score: 58) than in the adenoma regions (mean H-score: 110) of the samples (p = 0.02)." (PMID 32294981, 2020). "Enhanced EPHB3 expression in TAs declined during the transformation from adenoma to carcinoma, and it further decreased when the tumor began invading deeper into the muscular layers." (PMID 32294981, 2020). "However, EPHB3 expression completely disappeared during the adenoma–carcinoma transition in only one case." (PMID 32294981, 2020). "Furthermore, we analyzed alterations in the expression of EPHB3 during various stages of CRC progression: adenoma-to-carcinoma transformation, tumor budding, and lymph node metastasis." (PMID 32294981, 2020). "These animals are genetically inclined to form tens of adenomas in the small intestine and dysplastic crypts in the colon, accumulating b-catenin in their nucleus and upregulating the expression of the EPHB2, EPHB3, and EPHB4 genes." (PMID 35269901, 2022). "To further investigate the change in EPHB3 expression during CRC progression, we identified 22 CRC samples that included regions of carcinoma and of pre-existing adenomas." (PMID 32294981, 2020). "Additionally, EPHB3 expression was reported to be higher in CRC tissues compared with the adjacent normal mucosa and its expression was noted as downregulated during the conversion from adenoma to carcinoma." (PMID 35269901, 2022). "In line with the effect of Ap4 deletion in adenomas, GSEA indicated that mRNAs characteristic for Lgr5-positive ISCs and several factors involved in Wnt/β-catenin and Notch signaling pathways were preferentially downregulated upon deletion of Ap4: for example Sox4, Axin2, EphB3 were downregulated." (PMID 30177706, 2018).
glioma (6 papers, 2009 to 2025). A benign or malignant brain and spinal cord tumor that arises from glial cells (astrocytes, oligodendrocytes, ependymal cells). "EphB3 expression inversely correlates with glioma aggressiveness, decreasing progressively with tumor grade." (PMID 41200151, 2025). "In glioma cell lines such as U87MG and U251, low EphB3 levels are associated with increased proliferation, migration, and invasion, primarily through upregulation of EGFR and activation of the PI3K/AKT signaling pathway." (PMID 41200151, 2025). "Amplifications and mutations of PDGFRA, KIT and KDR were found in 8-15% of RMPAhigh gliomas, followed by EPHB3 (7.7%), FGFR1 (5.9%), FGFR3 (5.9%) and MET (4.1%)." (PMID 27385209, 2016). "Lukashova-v Zangen I el al. described that the overexpression of EPHB3 gene in ependymomas with high proliferation indices was associated with a poor outcome, and Kuraya el al. demonstrated the high expression of MASP1 gene in glioma cell line." (PMID 19607727, 2009). "We found that curcumol treatment decreased the binding ability of EZH2 to the promoter of downstream effectors (EphB3, p21, and CDKN1B) and the H3K27me3 modification in the promoter regions of effectors and increased the expression levels of effectors in glioma." (PMID 34739394, 2021). "As expected, curcumol significantly increased the levels of EphB3, p21, and CDKN1B in glioma cells." (PMID 34739394, 2021). "Our proteomic data suggested the disturbance of processes related to cell movement, highlighted by decreased levels of several proteins involved in glioma migration, such as CD9 and EPHB3 after treatment with Gos or ATO/Gos, as well as EPHA2 after treatment with GANT/Gos." (PMID 30871073, 2019). "Co-occurrence between amplification of EPHB3 and alterations in PIK3CA (both at chromosome 3q26-3q27), and amplifications in PDGFRA, KIT and KDR (all at 4q12) were also found in a subset of RMPAhigh gliomas, due to their localization in the common amplicons." (PMID 27385209, 2016). "The exceptions are three genes (NTRK2, EPHB3, and EPB41L2), which are known to play a role in neural systems, and only appear in some of the core modules from the two cancer types of neural origin, gliomas and melanoma, and NSCLC that expresses prominent features of neuroendocrine cells." (PMID 22691569, 2012).
lung carcinoma (6 papers, 2013 to 2022). "EphB3 encodes a receptor tyrosine kinase that suppresses AKT activation in lung cancer cells." (PMID 30683134, 2019). "EPHB3 is an ephrin-binding membrane receptor, which facilitates cell adhesion, enhancing the migration and promoting the metastatic behaviour of lung cancer cells." (PMID 34771489, 2021). "Interestingly, EphB3 also inhibits the migration of lung cancer cells." (PMID 30683134, 2019). "In particular, forward ephrin-B signaling via EphB3 can promote Akt dephosphorylation through protein phosphatase 2A (PP2A), leading to inhibition of lung cancer invasion." (PMID 35780836, 2022). "Like PTEN, EphB3 suppresses AKT activation and inhibits lung cancer cell migration." (PMID 30683134, 2019). "One possibility that could explain these discrepancies is the interface of Eph receptors with downstream networks that regulate tumorigenicity, such as that between EphB3 and the PP2A/RACK1/Akt axis in lung cancer." (PMID 23844053, 2013).
colorectal tumors (5 papers, 2006 to 2022). "In EphB3−/−; ApcMin/+ mice, they documented 30% more colorectal tumors, a two-fold increase in tumor size >5 mm in diameter, and a three-fold increase in the percentage of invasive disease in comparison with EphB3+/−ApcMin/+." (PMID 35269901, 2022). "Conversely there are clinical data showing that EphB3 and EphB2 expression is significantly reduced in advanced and spread colorectal tumors, suggesting a tumor suppressive function for these receptors." (PMID 32316101, 2020). "Furthermore, a pattern of inactivation similar to EPHB2 has been observed for EPHB4 and EPHB3 in colorectal tumors and/or cell lines, respectively." (PMID 16740153, 2006).